IGF1R (insulin like growth factor 1 receptor)
Diseases named in the same sentence as IGF1R in open-access papers (continued):
Sharing a sentence is not in itself a finding about the gene and the disease.
tumor (continued). "Mechanistically, PRKCSH interrupts TNFSF-mediated apoptotic signaling by promoting IGF1R activation in tumor cells without affecting the expression of TNFSF receptors, resulting in the inhibition of tumor cell death." (PMID 38200153, 2024). "Nonetheless, the effect of CR in reducing tumor burden persists, suggesting a possible non-IGF-1 mediated response or a reduction in tumor and peritumoral expression of IGF-1 or IGF1R." (PMID 39195514, 2024). "Contrary to the direct connection established between the IGF1R pathway and the regulation of EMT-TFs expression in other tumor types, we have not observed changes in EMT-TFs expression following IGF1R inhibition." (PMID 39075581, 2024). "RNA expression of GH, GHR, IGF1, IGF1R, and PRLR is also detected using qPCR, and IGF1 production in tumor cells is markedly lower in mouse tumor cells but not in human tumor cells." (PMID 39000545, 2024). "Furthermore, IGF-1R’s involvement in modulating the tumor microenvironment, including interactions with immune cells, suggests that combining IGF-1 inhibitors with immunotherapies could bolster anti-tumor immune responses, offering a multi-pronged approach to combat BC." (PMID 39273251, 2024). "Western blot analysis of the tumor samples further confirmed that panobinostat treatment increased the expression of HER3, but not EGFR or IGF-1R." (PMID 37537339, 2023). "Based on the co-expression of IGF1R and HER2, OncoLAR® was tested in combination with tamoxifen (NCT00001436), but there was no tumor response." (PMID 34440844, 2021). "Preclinical data concerning the combination of IGF1R and STAT3 inhibitors, but not IGF1R inhibition alone, showed a reduction in tumor burden through CAF and myeloid cell depletion." (PMID 34065119, 2021). "IGF1R and ISNR were not included in the C0376358 gene set, but were reported of the oncogenic functions including tumor growth, cell migration and angiogenesis in prostate cancer." (PMID 33772054, 2021). "We next investigated the molecular mechanisms by which IGF1R preferentially regulates the growth of tumor OPCs and why other GFs such as PDGF cannot effectively rescue the growth of tumor OPCs without the proper function of IGF1R." (PMID 33173731, 2020). "BMS-754807 exerts a strong antineoplastic effect on several cancer model cells, apparently in a way mostly independent of IGF-1R inhibition and is able to inhibit the ERK1/2 and PI3K/AKT/mTOR signaling pathways, which are crucial for tumor cells to survive." (PMID 33322337, 2020). "In a trial of the IGF-1R mAB [IMC-A12] ± cetuximab in metastatic colorectal carcinomas (MCRC), 1/41 patients had a partial tumor response (PR) with combined therapy, while no antitumor activity was observed in the monotherapy arm." (PMID 29843755, 2018). "Further, exogenous rIGF‐2 was able to restore migration in IGF‐2R‐RNAi‐transfected MSCs, but not in IGF‐1R‐RNAi‐transfected cells, demonstrating that IGF‐1R is probably more important for MSC tumor tropism than IGF‐2R." (PMID 29321953, 2018). "Measurement of IGF1R and HMGA2 protein levels in 15 HNSCC tumor tissues and adjacent non-tumor tissues showed significantly higher levels of both proteins in the HNSCC tumor tissues than in the non-tumor tissues." (PMID 29507664, 2018). "Tumor tissue from mice treated exclusively with MSM exhibited reduced expression of IGF-1, STAT3, STAT5b, and VEGF without significant suppression of IGF-1R." (PMID 28300758, 2017). "We further demonstrated that this effect is not restricted to the tumor process and that SLPI and CTGF expression is directly regulated by IGF1R." (PMID 27179633, 2016). "Strikingly, the primary tumours were either completely negative (L835, CH2879) or showed weak staining (L3252B, L2975) for IGF1R." (PMID 27418340, 2016).
tumor (continued). "Therapy with MEK inhibitor U0126 produces only a transient inhibition of tumor glycolytic activity but does not inhibit tumor growth, which is due to continuing IGF2-induced signaling from IGF1R through the PI3K-AKT-mTOR pathway." (PMID 22875335, 2013). "Therapy with MEK inhibitor U0126 produces only a transient inhibition of tumor glycolytic activity but does not inhibit tumor growth, which is most likely due to continuing IGF2-induced signaling from IGF1R through the PI3K-AKT-mTOR pathway." (PMID 22875335, 2013). "In the cixutumumab trial, patients were evaluated for tumor levels of IGF-1, IGF-2, and IGF-1R by immunohistochemistry, and the study reported no apparent correlation between expression of these three proteins and response to cixutumumab treatment." (PMID 23431249, 2013). "In contrast, mTOR, IGF1R and JAK/STAT pathways appeared to be primarily important for growth, branching and differentiation of both normal and tumor cells, regardless of the cell culture conditions, ECM and the microenvironment." (PMID 20454659, 2010). "4T1.2 cells expressed the IGF1R and IGFBP4, but not the IGFBP4 protease PAPP-A, although PAPP-A was expressed within 4T1.2 mammary fat pad tumours." (PMID 19536088, 2009). "Preclinical studies from Sanofi-aventis (Paris, France) have shown that there is no direct correlation between the antiproliferative effect of a human anti-IGF1R antibody, AVE-1642, and the level of IGF1R in more than 90 tumour cell lines (data not shown)." (PMID 19491901, 2009). "Thus, QDs could localise to the tumour, but the localisation was not specific for IGF1R expression." (PMID 19491901, 2009). "This is expected as anti-IGF-1R therapy disrupts the negative feedback loop at the hypothalamic–pituitary axis, leading to elevated circulating growth hormone which can upregulate IGF-1R expression and other downstream pathways that sustain tumor growth." (PMID 41347090, 2025). "We can hypothesize that IR, expressed as the mitogenic IRA isoform in these tumours, coupled with the overexpression of IGF2 in ACC, but not in ACA, can sustain the growth of ACC cells more than IGF1R." (PMID 40038716, 2025). "In addition, the inhibition of IR and/or IGF1R signaling in PTENKO mice also tended to reduce tumor number and total tumor volume, whereas the average tumor volume was not statistically different between the mutant mice." (PMID 40115165, 2025). "Exploring the interplay between IGF1R, IR, and other components of the IGF system, will be essential to better understand the compensatory mechanisms that may drive tumor growth in the absence of IGF1R or IR activity." (PMID 40038716, 2025). "According to this, the targeting of IGF-1 or IGF-1R will not stop the action of PEc, which apart from inducing cellular proliferation and EMT leading to metastasis and invasion also induces the recruitment of mesenchymal stem cells prior to tumor repair." (PMID 39273251, 2024). "Collectively, these results suggested that, at least in the tumor microenvironment, IGF1 bioavailability was not compromised by protein restricted diet and could still activate IGF1R overexpressing Mir15aKO PDAC." (PMID 38342897, 2024). "The combination of sorafenib and niclosamide, but not linsitinib, effectively suppressed the IGF-1R/OCT4 expressions, yielded a synergistic combination index (CI), and attenuated stemness-related properties such as secondary tumor sphere formation and cell migration in sorafenib-resistant HCC cells." (PMID 36765890, 2023). "Indeed, we found that metronomic DOX treatment suppressed mTORC1-dependent translation of angiogenic Vegfr-2/3 mRNAs but not Igf-1r and Egfr mRNAs containing an IRES27,38, thereby attenuating tumor growth and metastasis." (PMID 34697389, 2021).
tumor (continued). "Moreover, pathway activity is altered during culture, for instance we previously showed upregulation of IGF1R expression in CH2879 cell line in 2D culture, while this was not seen in three-dimensional (3D) cultures, nor in the corresponding primary tumor." (PMID 33425984, 2020). "However, no marked correlation was observed between circ‐IGF1R expression and other clinical pathological factors, including sex, age, smoking, subtype, and pathologic TNM (Tumor, Node, Metastasis) stage." (PMID 32107851, 2020). "The non-tumor regions of all HCCs stained negative for GPC3 and IGF-1R." (PMID 29113314, 2017). "To elucidate the discrepancy between the observed protein expression of IGF1R in cell lines and the absence of an effect of IGF pathway inhibition, we assessed IGF1R expression in clinical tumour samples versus cell lines that were formalin-fixed and paraffin-embedded (FFPE)." (PMID 27418340, 2016). "In order to further investigate whether CD24 cell surface expression could implicate tumor sensitivity to anti-IGF1R therapy, we inoculated CD24- and CD24+ cells with and without IGF1R-KD into the mammary fat pad of WT and the hyperinsulinemic MKR female mice." (PMID 27179633, 2016). "We further demonstrate that this differentiation process toward the CD24- phenotype in the CD24+/IGF1R-KD is significantly enhanced as a result of the tumor microenvironment; the distribution of CD24- and CD24+ subsets was not affected in vitro as a result of the IGF1R-KD." (PMID 27179633, 2016). "These analyses showed that 29 out of the 48 patients (60.4%) suffering from tumour stages III-IV and negative or fairly positive MVP/IGF-1R expression were alive, while 3 out of the 18 patients (16.7%) with tumour stages III-IV and overexpression of MVP and IGF-1R were alive (P = 0.002)." (PMID 22931894, 2012). "It is likely that a suite of biomarkers, both in the host and tumor will be required rather than single biomarker selection, with some candidates for study in RMS including IGF2, pIGF1R/IGF1R, IGF1, pIRS-1/IRS-1, pIR-A/IR-A, IGFBP-6, and maybe others such as HSPs, PDGFR and Erb2." (PMID 21437217, 2011).
cancer (1,375 papers, 2004 to 2026). A tumor composed of atypical neoplastic, often pleomorphic cells that invade other tissues. "IGF1R inhibitors have all failed in cancer clinical trials, and IR-A function has been proposed as a potential compensatory mechanism for loss of IGF1R signaling." (PMID 40303997, 2025). "Because of the greater possibility of metastasis, it was discovered that overexpression of IGF1R is actually linked to higher mortality in the majority of cancer patients." (PMID 39434498, 2025). "The higher expression of IGF-1R was reported to promote cancer cell proliferation and lead to an increased risk of death for ccRCC patients." (PMID 40622919, 2025). "MA exerts its anticancer effects by targeting key proteins such as EGFR, SRC, HSP90AA1, MDM2, and IGF1R, which are often overexpressed or mutated in resistant cancer cells." (PMID 40070571, 2025). "Citrate accumulation has been associated with the suppression of cancer proliferation through inhibition of the IGF-1R/AKT pathway, while the accumulation of succinyl-CoA, succinate, and fumarate has been linked to epigenetic regulation in cancer." (PMID 41154474, 2025). "The association between FLOT1 and the IGF1R triggers anti-apoptotic signaling pathways, suggesting their role in activating signaling pathways in human cancers." (PMID 40335491, 2025). "Intriguingly, cancer‐associated fibroblasts‐secreted IGF‐1 upregulates QSOX2 expression via IGF1R/Akt/mTOR/c‐Myc pathway, establishing a positive feedback loop that sustains ESCC cell stemness." (PMID 40433832, 2025). "High levels of IGF-1R can cause resistance across different cancers, and cancer cells can become resistant to IGF-1R inhibitors, by activating PI3K/mTOR pathways through alternative EGFR signaling." (PMID 41427337, 2025). "The IGF1R, a receptor tyrosine kinase located on the cell membrane, has been associated with promotional effects on cancer development when overexpressed." (PMID 40530890, 2025). "Overexpression and activation of IGF-1R has been reported to be associated with a high risk of metastasis and poor prognosis in many cancer patients." (PMID 38342894, 2024). "Using monoclonal antibodies, small molecule tyrosine kinase inhibitors, and IGF-1R mutations and silencing are four common anti-cancer strategies targeting the IGF signaling system." (PMID 38540176, 2024). "In the IGF1R, three cancer associated mutations were described by Craddock and Miller, two of them in the C-terminus (DS1278 and A1347V) and one in the C-terminal lobe of its catalytic domain (M1255I), mutations that disrupt the downstream signaling cascade." (PMID 39138146, 2024). "IGF1R signaling has been extensively implicated as a pivotal factor in cancer cell proliferation, survival, migration, and resistance to anticancer therapies." (PMID 39328205, 2024). "Reduced expression or inhibition of the IGF1R is associated with defects in DNA repair mechanisms in other settings, sensitizing cells to cytotoxic drugs and radiation treatment in cancer therapy." (PMID 38706850, 2024). "IGF1/IGF1R pathway has been implicated in various aspects of cancer biology, such as cell transformation, EMT induction, invasion or metastasis, making it a desirable oncology therapeutic target." (PMID 39075581, 2024). "IGF-1R activation has been also associated with increased cancer cell migration and invasion in various cancer types." (PMID 39328205, 2024). "We previously proposed that this phosphorylation is associated with cell migration and cancer aggressiveness, distinguishing IGF-1R activity from that of insulin receptor, which lacks these tyrosines." (PMID 39608716, 2024). "The insulin-like growth factor 1 receptor (IGF1R) has been associated with growth and metastasis in various cancers." (PMID 39365756, 2024). "STAT3 has been recognized as the canonical downstream signaling of IGF1R, and the IGF1R/STAT3 signaling axis has been associated with the development of cancer chemoresistance." (PMID 39394189, 2024).
cancer (continued). "Dysregulated IGF1R signaling due to missense mutations can contribute to uncontrolled cell growth and reduced apoptosis, which are characteristic features of cancer development and progression." (PMID 38737102, 2024). "Multiple studies have shown that the protective effect of CR in cancer progression are associated with its regulation of IGF1R signal pathway." (PMID 37686596, 2023). "The data indicated that HSP90AB1 likely interacts with IGF1R, which is also associated with cancer cell growth and death." (PMID 37180757, 2023). "IGF-1R overexpression is associated with an increased risk of developing cancers, including HCC, and the expression and activation of IGF-1R are related to drug resistance in tumors." (PMID 36698167, 2023). "A wide variety of human cancers have been linked to the overexpression of insulin receptors and IGF-1R resulting from transcriptional dysregulation." (PMID 38034011, 2023). "There is a strong positive association between high levels of IGF-1R pathway signaling and cancer, though activating mutations of the IGF-1R gene have not been reported." (PMID 37858153, 2023). "High expression of IGF-1R is closely associated with cancer stemness properties and sorafenib resistance in HCC." (PMID 36765890, 2023). "Under pathological conditions (e.g., energy deficiencies, starvation, hypoxia, cancer), IGF-1R signaling promotes autophagy/mitophagy." (PMID 36835075, 2023). "Among genes with IRESs identified in their 5’UTR, we took an interest in MYC and IGF1R, which are closely associated with cancer stem cell properties." (PMID 37891494, 2023). "Inhibition of nuclear IGF-1R kinase activity with NVP AEW-541 reduced expression of the transcription target gene SNAI2 that is associated with cancer cell invasiveness and metastasis." (PMID 37858153, 2023). "IGF1R signaling has been profusely implicated as a critical contributor to cancer cell proliferation, survival, migration, and resistance to anticancer therapies, thus targeting IGF signaling is an attractive therapeutic strategy." (PMID 35688943, 2022). "IGF-1R signaling is also implicated in cancer development due to its stemness-related properties and the resistance of radiation therapy and chemotherapy." (PMID 36233084, 2022). "Patients with high IGF1R expression experience significantly poorer cancer-specific survival, with a 70% increased risk of death." (PMID 36289686, 2022). "Despite increased stimulation of the IGF-1R by glargine, epidemiologic data on the association of glargine with cancer has been mixed." (PMID 35158824, 2022). "Via activation of the IGF1 receptors (IGF1R) and variant insulin receptors, IGFs promote cancer progression, aggressiveness, and treatment resistance." (PMID 36193308, 2022). "Nuclear IGF-1R staining is associated with more aggressive tumors and poorer survival outcomes in many types of cancer." (PMID 36556357, 2022). "IGF‐1R over‐expression in breast cancer cell lines has been shown to be associated with anti‐apoptotic mechanisms, and increased cancer cell invasion, specifically with up regulation of MMP's and activation of EMT in Estrogen receptor alpha positive cells." (PMID 34313032, 2022). "The interaction between MUC1 and IGF-1R causes IGF-1R to become a powerful angiogenic factor in cancer cells." (PMID 33836774, 2021). "As IGF-1R has been implicated in several cancer types it has garnered a great deal of interest as a therapeutic target." (PMID 33816477, 2021). "In this study, we identified the association between PKM2 and the expression of IGF-1R protein in cancer cells, particularly under hypoxic conditions." (PMID 34359752, 2021).